CRP (C-reactive protein)
Diseases named in the same sentence as CRP in open-access papers (continued):
Sharing a sentence is not in itself a finding about the gene and the disease.
diabetes (continued). "Numerous controlled human studies demonstrate that successful periodontal treatment reduces circulating C-reactive protein (CRP) and tumor necrosis factor (TNF)-α levels in subjects with diabetes, proving its active role in inflammation." (PMID 36832168, 2023). "Higher age, c-reactive protein level and LAD, comorbidities including hypertension, diabetes and coronary heart disease, smoking history, centric pulmonary carcinoma and pericardial effusion were also associated with higher risk of NOAF in univariate analysis." (PMID 37519821, 2023). "Adjusted variables included age, sex, CRP, HGB, LDL-c, HDL-c, TG, FPG, HCT, HBA1c, hypertension, diabetes, SBP, CKD, CHD, mental illness, CLD, drinking status, and smoking status." (PMID 37484946, 2023). "The ECW/ICW ratio was positively correlated with age, male sex, history of diabetes, CTR, and log CRP and was negatively correlated with the GNRI and SCI." (PMID 36897875, 2023). "Additionally, this study revealed an association between CRP levels and periodontitis in an obese population, independent of age, sex, race, marital status, annual family income level, alcohol consumption, hypertension, smoking status, COPD, cardiovascular disease, diabetes, flossing, and arthritis." (PMID 37481511, 2023). "Diabetes, drinking, SBP, DBP, mean arterial pressure (MAP), mRS score, and laboratory indexes such as Hs-CRP, FA, VB12, uric acid (UA), Hcy, TG, HDL, and TSH showed significant differences between the ISHH and the NISHH groups." (PMID 37954644, 2023). "When we excluded participants with the history of CHD, stroke, diabetes, and hypertension from the mediation analysis, LDL, triglycerides, and CRP still significantly mediated the cognitive effect of statin but HDL, blood glucose, and vitamin D did not." (PMID 37431946, 2023). "Intracellular water was associated with sarcopenic obesity in chronic HD patients independent of dialysis vintage, age, history of CVD, history of stroke, history of diabetes, usage of L- carnitine, SBP, DBP, haemoglobin, albumin, triglyceride, BMI and CRP." (PMID 37803331, 2023). "Factors tested using multivariate analysis, i.e. age, C-reactive protein, D-dimer, albumin, body temperature, Sequential Organ Failure Assessment (SOFA) score, and diabetes." (PMID 37767018, 2023). "Elevated levels of PCT, CRP, NEUT and decreased levels of PLT and ALB were observed from patients with diabetes in the severe group, where level of N increased both quantitatively and as a categorical variable." (PMID 37790212, 2023). "C-reactive protein (CRP) and interleukin-6 (IL-6) are significantly elevated in patients with diabetes, hypertension, and the metabolic syndrome." (PMID 37894687, 2023). "This scoring system considers factors such as age, systolic blood pressure, diabetes mellitus, and smoking, as well as levels of TC, HDL-C, and CRP." (PMID 37760885, 2023). "Age, diabetes, CRAO, neutrophil count, lymphocyte count, NLR, LDL-C, and hs-CRP were predictors of MACCE in univariate Cox analysis (all P < 0.05)." (PMID 37696870, 2023). "Univariate Cox analysis showed that age, diabetes, current smoking status, CRAO, neutrophil count, NLR, LDL-C and hs-CRP (all P < 0.05) were predictors of MACCE." (PMID 37696870, 2023). "This review has found that the most common variables for predicting post-PCI MACE include LVEF, age, Killip classification, diabetes, Cr, BNP, gender, troponin, smoking, hypertension, and CRP." (PMID 38259313, 2023). "CAD: coronary artery disease; CRP: c-reactive protein; IL6: interleukin 6; MDA: malondialdehyde; T2DM: type 2 diabetes mellitus; TAC: total antioxidant capacity; TNF-α: tumor necrosis factor-alpha." (PMID 38034261, 2023). "Tertiles of net financial wealth and CRP (>3 mg/L) were measured at wave 2 (2004/05) and disease incidence (coronary heart disease [CHD], stroke, diabetes/high blood glucose) was reported across the subsequent 14 years of follow-up (2006–2019)." (PMID 37808231, 2023).
diabetes (continued). "Fourth, some risk factors, such as sedentary activity, low birthweight, C-reactive protein, and urinary cadmium, were not considered because they were not available or collected in subsamples or specific cycles only, or had bidirectional or controversial associations with diabetes." (PMID 37213641, 2023). "Five potential predictors of PDAP after PD catheterization were screened using LASSO regression analysis, including neutrophil-to-lymphocyte ratio (NLR), serum ALBumin (ALB), uric acid (UA), high sensitivity C-reactive protein (hsCRP), and diabetes mellitus (DM)." (PMID 37790129, 2023). "A 2 g intake of FO for the 14-week period tended to decrease fasting blood glucose, C reactive protein, and TNF-α levels in overweight adults with pre-diabetes." (PMID 37685162, 2023). "Previous studies have demonstrated a range of associations between erectile dysfunction (ED) and various indicators, such as age, BMI, smoking frequency, hypertension, diabetes, CVD, and some inflammatory indices like leukocytes and CRP." (PMID 37424870, 2023). "In univariate regression analysis, the highest CRP, subcutaneous fat thickness, LPM fat infiltration, diabetes, UTIs, occupation and surgery duration showed statistically significant differences." (PMID 36788621, 2023). "The results showed that PIV was significantly associated with all-cause mortality in patients undergoing PD, after subgroups of patients based on their sex, age, diabetes history, CVD history, CRP level, albumin level, and eGFR (all p < 0.05)." (PMID 36632816, 2023). "The study aimed to determine hematological indices, ESR, CRP, blood pressure (BP), and weight and their relationship with a fasting blood sugar (FBS) level and different variables in diabetic mellitus patients (DM) compared with healthy control (HC)." (PMID 37794107, 2023). "Successful periodontal treatment has been shown to lower the circulating levels of C-reactive protein (CRP) and tumor necrosis factor (TNF)-α in people with diabetes, providing further evidence of its active role in inflammation." (PMID 38132485, 2023). "The CRP-diabetes association could not be fully explained by obesity or hypertension." (PMID 37775289, 2023). "These variables were age, WC, BMI, AST, ALT, CRP, SBP, DBP, presence of hypertension, and presence of diabetes in men." (PMID 37409278, 2023). "The C-index predicting all-cause death improved significantly from 0.788 to 0.835 (p = 0.038) when adding ECW/TBW ratio to the baseline risk model, which included age, sex, hemodialysis vintage, history of diabetes and CVD events, CRP, and PEW." (PMID 37652929, 2023). "Oral administration of genistein (300 mg/kg/day) in streptozotocin (STZ)-induced diabetic rats showed decreasing in C-reactive protein, HbA1c, blood glucose, and expression of TGF-β1 and NF-α proteins that were increased in STZ-induced diabetes." (PMID 37275572, 2023). "Predictors reported were patients’ age, sex, presence of hypertension and diabetes, fever, short-ness of breath, serum glucose, AST, respiratory rate, NLR ratio, LDH, systolic blood pressure, CRP and fibrinogen." (PMID 36840867, 2023). "The participants in the overweight/obese-high VF group were younger, had higher SBP, DBP, Hs-CRP, TG, FINS, INS2h, FCP, CP2h, FPIS, SPIS, HOMA2-IR, shorter diabetes duration, lower HDL and Gutt-ISI compared to the normal weight-normal VF group (all p < 0.05)." (PMID 36909323, 2023). "Various other clinical characteristics such as mean age, percent women, body mass index, smoking status, history of diabetes, history of cardiovascular disease, and mean IL6 and CRP levels were also investigated by sRAGE levels." (PMID 37198231, 2023). "After adjusting gender, BMI, heart failure, diabetes, LAD, and CRP, PNI < 46.4 (OR: 2.457, 95% CI:1.333–4.526, P = 0.004) and GNRI < 105.7 (OR: 2.113, 95% CI:1.076–4.149, P = 0.030) remained independent predictors of LAT." (PMID 37891483, 2023).
diabetes (continued). "After multiple imputation for missing variables, sex, age, dialysis duration, diabetes, BMI, BUN, Cr, Alb, CRP, Hb, use of icodextrin and UV were all found to be independent factors affecting serum B2M." (PMID 35421178, 2022). "Several pro-inflammatory markers, such as C-reactive protein, IL-1b, IL-6, IL-8, and TNF-α, are elevated in migraine and diabetes." (PMID 36498528, 2022). "The parameters which helped in identifying the severity, leading to poor prognosis, were neutrophil:lymphocyte higher than 4, high CRP, low SOD3 values and high GSTp1 values, and diabetes mellitus as a co-morbidity." (PMID 35314591, 2022). "Given the confounding effect that using A1c as a BA biomarker has in prediabetes and diabetes, recalculation of BA using KDM was done by excluding A1c and substituting it with CRP, a commonly used biomarker with a high correlation to CA." (PMID 34773197, 2022). "LDL-C and diabetes mellitus had a strong correlation with MACE, while age and hs-CRP were weak correlation factors for MACE." (PMID 36348286, 2022). "A univariable analysis revealed nine variables to be included in the model: random blood glucose, years with diabetes, cardiovascular diseases, peripheral arterial diseases, DFU history, smoking history, albumin, creatinine, and C-reactive protein." (PMID 36472981, 2022). "GlycA has been associated with impaired insulin secretion and is a better predictor for incident diabetes and cardiovascular events than CRP (C-reactive protein) and interleukin-1 receptor antagonist." (PMID 35399690, 2022). "Adding log RBP4 to a basic riskmodel including age, BMI, diabetes duration, LVEF, insulin treatment, TG, LDL-C,eGFR, CRP, log NT-proBNP, retinopathy, nephropathy and neuropathy improved thec-index from 0.91 to 0.94 (p = 0.024)." (PMID 39076230, 2022). "Notable differences were observed in their demographic and laboratory parameters, including heart failure, peripheral vascular history, hypertension, diabetes mellitus, SBP, HDL-C, BUN, sCr, hs-CRP, and TB levels." (PMID 35300593, 2022). "The AUC of Model 1 containing risk factors (including age, gender, hypertension, hyperlipidemia, diabetes, smoke, LDL, Hs-CRP, LVEF) was 0.780 (95% CI: 0.738–0.819)." (PMID 36547463, 2022). "Ten parameters with non-zero coefficients were screened: hypertension history, CAD, diabetes, SaO2, ALT, lactate, PCT, CRP, SCR, and GFR." (PMID 36505004, 2022). "The association remained unchanged after further adjustment for smoking, BMI, BP treatment, SBP, diabetes, total cholesterol, HDL cholesterol, triglycerides, blood glucose and CRP (Model 2)." (PMID 36560680, 2022). "At present, CRP, IL-6, and TNF-α are recognized as representative markers of inflammatory factors in patients with diabetes, which can damage EPCs’ function, and reduce endothelial regeneration and vascular repair." (PMID 36199064, 2022). "We explored the source of heterogeneity using clinically important variables (diabetes mellitus, hypertension, cardiac disease, total WBC count, neutrophil count, CRP, and cut-off value of PCT) on the effect size." (PMID 36084093, 2022). "The present study showed that Hcy was independently associated with S among older hospitalized adults after adjustment for age, gender, education, smoking, BMI, MNA-SF, ALT, CRP, Hb, ALB, diabetes, kidney disease, and statin use." (PMID 36424548, 2022). "Consistent with previous reports, findings in this research showed that subjects with diabetes and CAD had higher levels of WBC, NEU, NLR, hs-CRP and GDF-15 than those with T2DM alone, indicating a more severe inflammatory state." (PMID 35842724, 2022). "We report on the beneficial effects of NBF1, an algal fiber-rich formula, on CRP, APN, and diabetes markers." (PMID 36289836, 2022). "Multivariate adjusted: The variables with p < 0.05 in univariate analysis were adjusted, including age, diabetes, LDL-C and hs-CRP." (PMID 36348286, 2022).
diabetes (continued). "Preoperative baseline hs-CRP level, LDL-C level, NLR, diabetes, lesion length, and long-term postoperative rivaroxaban were predictors of restenosis within 1 year after intervention." (PMID 35911526, 2022). "Adjusted means of ln (homocysteine) level in the groups were estimated from ANCOVA after adjustments for age, sex, history of hypertension, history of diabetes, HDL-C, ALT, and CRP." (PMID 35858996, 2022). "In COX regression analysis, the incidence of cardiovascular events in five years was taken as dependent variables, and age, sex, drinking, smoking, hypertension, diabetes, HDL-C, LDL-C, CRP, CIMT, and serum SOX2-OT were taken as independent variables." (PMID 35538435, 2022). "There was a significant difference between the incident CVD and non-CVD group in age, sex, education, income, smoking, drinking, hypertension, diabetes, dyslipidemia, medications, SBP, DBP, FBG, TC, TG, HDL-C, LDL-C, and hs-CRP." (PMID 36564775, 2022). "Multivariate analysis revealed the correlation between GSDMD level and diabetes, LDL-C, TC, CRP, WBC, RDW and LVEF in AMI." (PMID 36544106, 2022). "Variables (gender, diabetes duration, PAD, hs-CRP, and HbA1c) with a univariate P ≤ 0.1 were considered as potential confounders." (PMID 35320298, 2022). "Results showed that age, diabetes mellitus, hypertension, ASA scores, CRP, Alb, CAR and the operation time was an independent predictor for patients with POD." (PMID 36051706, 2022). "For Below Severe vs. Critical model, 6 predictors were finally selected as the final model: CRP, respiration rate, chronic kidney disease, AST, age, and diabetes." (PMID 36518574, 2022). "Similarly, this was observed for patients with diabetes mellitus (DM), atrial fibrillation (AF), higher hs-CRP, and higher serum cortisol." (PMID 33724085, 2022). "The univariate analyses showed that MAFLD, age, DM, prediabetes, hypertension, overweight/obesity, waist circumference, BFP, hyperuricemia, hypertriglyceridemia, HDL-C, remnant cholesterol, CRP, FIB-4 score, and NFS were significantly associated with an increased risk of CKD (p < 0.05)." (PMID 36374233, 2022). "The mean serum ACE (92.35±10.28), oxLDL (48.59±8.56), hs-CRP (5.87±1.62), MMP-9 (89.20±30.19), and MDA (1.146±0.198) levels were significantly (p-value <0.0001) higher in smokers with CHD and diabetes (group 3) when compared to group 1 and group 2." (PMID 36110446, 2022). "In the highest uric acid quartile, the OR was 2.91 (95% CI: 1.54–5.51, P = 0.003 for trend) for MetS after further adjusting for alcohol drinking, smoking, duration of diabetes, self-reported CVD, BMI, CRP, HbA1C, FBG, eGFR, TC, and LDL-C." (PMID 35769075, 2022). "These variables include age, creatinine, WBC, lymphocyte/neutrophil count, BUN, ASP, ALT, LDH, activated PTT, coughing, hypertension, CVD, diabetes, dyspnea, oxygen therapy, pneumonia, GI complications, ESR, and CRP." (PMID 36494613, 2022). "In another study conducted by Wang and colleagues comprising patients with diabetes mellitus, LDH, PCT, CRP, ferritin, and IL-6 were significantly increased in ICU patients compared to non-ICU patients." (PMID 35746755, 2022). "In addition, we found that the prevalence of diabetes was higher in the group with elevated CRP than in the normal group, and although it was not statistically significant, diabetes was positively associated with the development of hypertension (OR = 2.68,95%CI:1.24–5.79, P < 0.05)." (PMID 36418968, 2022). "Participants with DR had elevated CRP, HbA1c, neutrophil counts, NLR, diabetes duration, and lower lymphocyte counts." (PMID 35978314, 2022). "Patients in the highest quartile (quartile 4) tended to be older, suffered more from diabetes, were more likely to have higher BMI, TC, TG, LDL-C, and hypersensitive C-reactive protein (hs-CRP) levels but lower serum albumin and HDL-C levels." (PMID 35399692, 2022).
diabetes (continued). "This is evidenced by several clinical studies showing that serum OCN level was negatively correlated with systemic inflammatory markers, such as interleukin-6 (IL-6) and C-reactive protein (CRP), in patients with diabetes, obesity, or metabolic syndrome." (PMID 35625743, 2022). "After adjusting for age, sex, BMI, WC, HOMA-IR, CRP, FPG, 2hPG, ALT, AST, GGT, hypertension, diabetes, and dyslipidemia, higher NC at baseline was a positive factor for the occurrence of MAFLD (OR 1.96, 95% CI: 1.21–3.31, p < 0.01)." (PMID 35858581, 2022). "This study aimed to identify the correlation between hs-CRP levels and diabetic kidney disease (DKD) in patients with type 2 diabetes mellitus (T2DM)." (PMID 35784528, 2022). "Further logistic univariate and multivariate analysis showed that baseline hs-CRP level, lesion length, use of rivaroxaban, NLR, LDL-C levels, and diabetes mellitus were predictors of restenosis." (PMID 35911526, 2022). "We performed a full adjustment for tubal ligation in Model 2 with age, hypertension, diabetes, LDL, HDL, TG, BMI, WHR, Hs-CRP, ECAS, and menopause." (PMID 35310999, 2022). "Adjustment was made for sex, age, body composition, pack years smoked, C-reactive protein, statin use, use of ACE inhibitors or ARBs, and diabetes." (PMID 35476713, 2022). "The FPG, 2hPG, TG, HbA1C, CRP, IL-6, visfatin, JAZF1, HOMA-IR, baPWV, and EAT thickness of the Diabetes Group were all higher than those of the Healthy Control Group, with statistical significance (P < 0.05)." (PMID 33722242, 2021). "Predicting factors included age; features derived from the CT machine; lactate dehydrogenase; sex; C-reactive protein (CRP); comorbidity, including hypertension, diabetes mellitus, cardiovascular disease, and respiratory disease; and lymphocyte count." (PMID 33455900, 2021). "Compared to the NGT participants, those with prediabetes or diabetes were older and had higher frequencies of hypertension and dyslipidemia and higher levels of triglycerides, total cholesterol, LDL, CRP, and BMI and a lower level of HDL." (PMID 34527591, 2021). "Hence, CRP could be an epiphenomenon in the development of CAS-related diabetes." (PMID 34104095, 2021). "In the present study, baPWV was positively correlated with age, duration of diabetes, BMI, waist circumference, MAP, FPG, 2hPPG, HbA1c, TG, hs-CRP, and UACR and negatively correlated with HDL-C." (PMID 33628837, 2021). "Finally, CRP was included among the covariates that masked the association of the insulin sensitivity index or fasting insulin concentration with all-cause mortality in older adults without diabetes." (PMID 33715620, 2021). "All these participants were free of diabetes at baseline and had high-sensitive C-reactive protein (hs-CRP), serum FA composition, and selected lipid metabolites measured during the active study period." (PMID 34960007, 2021). "Some studies have also stated that the C-reactive protein (CRP) level is a marker for dyslipidemia, diabetes, and MetS." (PMID 35317114, 2021). "Heart failure patients with age ≥70 years, diabetes, NYHA grade III, LVEF ≤55%, and CRP ≥10 mg/L have higher risks of pulmonary infections, preventive measures targeted on those risk factors are needed to reduce pulmonary infections." (PMID 34559121, 2021). "On the contrary, progressors to CV events (CV+/DM−) and diabetes (DM+) were older, and had a higher baseline SBP, glucose, insulin, HOMA index, creatinine, and hs-CRP mean values, while e-GFR and HDL-cholesterol values were lower." (PMID 34201832, 2021). "In our preoperative study model, gender, smoking, diabetes mellitus, HT, COPD, stroke, emergency, age, BMI, blood glucose level, preoperative albumin, troponin, CRP, ejection fraction (EF) and FEV1 values were included and evaluated." (PMID 34236782, 2021).